TNF (tumor necrosis factor)
Diseases named in the same sentence as TNF in open-access papers (continued):
Sharing a sentence is not in itself a finding about the gene and the disease.
Obesity (continued). "Obesity and psoriasis exhibit similar systemic inflammatory profiles, with elevated serum levels of cytokines such as TNF-α, IL-6, and IL-12." (PMID 40219010, 2025). "In obesity, there is a decrease in beneficial adipokines and an increase in pro-inflammatory factors, such as TNF-α, both of which promote the proliferation of VSMCs and inflammatory responses within PVAT." (PMID 40943241, 2025). "Current understanding of obesity’s impact on inflammatory arthritis centers on adipose tissue as an endocrine organ producing systemic pro-inflammatory mediators including TNF-α, IL-6, and leptin, which have the potential to fuel local synovial inflammation." (PMID 41227037, 2025). "TNF-α is a classic pro-inflammatory cytokine secreted by adipose tissue, immune cells, and others, playing a central role in obesity, insulin resistance, and metabolic disorders." (PMID 40661082, 2025). "In contrast, resistin levels are elevated in obesity and have been shown to promote insulin resistance and the release of pro-inflammatory cytokines such as TNF-α and IL-6." (PMID 41155642, 2025). "Both biological materials showed increased levels of TNF-α compared to healthy women, both systemically and locally, and confirmed the correlation with obesity, IR and androgen status in these patients." (PMID 40647668, 2025). "The inflammatory state is not limited to the local fat, but cytokines also enter the bloodstream and a range of pro-inflammatory cytokines, including IL1B, IL17A, IL-2, IFNalpha, gamma and TNF are increased in peripheral blood of individuals with obesity." (PMID 41227037, 2025). "Circulating levels of TNFα are increased in obesity, type II diabetes and fatty liver disease; TNF clearly impairs insulin signaling." (PMID 40766326, 2025). "The Tumor Necrosis Factor (TNF)-alpha overexpression in adipose tissue plays important roles in mediating obesity and insulin resistance." (PMID 39985597, 2025). "In our cohort, individuals with obesity showed elevated plasma Ang II, heightened concentrations of IL-1β, IL-6, and TNF, and reduced IL-10, supporting the presence of a dysregulated inflammatory state exacerbated by viral infection." (PMID 41562075, 2025). "Shift from M1 to M2 Macrophages: In obesity, adipose tissue is characterized by an infiltration of proinflammatory M1 macrophages, which secrete cytokines such as TNF-α and IL-6, contributing to systemic inflammation and insulin resistance." (PMID 40863154, 2025). "For example, adipokines such as leptin and adiponectin regulate energy homeostasis and lipid metabolism, while inflammatory markers like TNF‐α and IL‐6 highlight the role of chronic inflammation in obesity." (PMID 40551726, 2025). "Adipose expansion in obesity promotes dysregulated adipokine secretion and macrophage infiltration, leading to release of inflammatory mediators such as IL-6 and TNFα." (PMID 41400625, 2025). "Adiponectin also has anti-inflammatory properties, opposing the actions of proinflammatory cytokines, such as TNFα, which are increased in obesity." (PMID 40013194, 2025). "Studies have shown that obesity induces baseline elevation of proinflammatory cytokines such as IL-6 and TNF-α in the brain, with heightened levels in the cortex and hippocampus." (PMID 40216734, 2025). "A study investigating its anti-obesity potential in 3T3-L1 adipocytes showed that harpagoside inhibited tumor necrosis factor-α (TNF-α)-induced adipokine expression by activating of peroxisome proliferator-activated receptor gamma (PPAR-γ)." (PMID 41226163, 2025). "Obesity promotes systemic inflammation through elevated cytokines such as interleukin-6 (IL-6) and tumor necrosis factor-alpha (TNF-α), leading to airway inflammation and hyperresponsiveness." (PMID 41244254, 2025). "The proportion of M1 macrophages in adipose tissue increases from 4% up to 12% as obesity progresses, leading to the release of inflammatory cytokines such as IL-1β, TNFα, and IL-6, that sustain a chronic inflammatory state." (PMID 41156032, 2025).
Obesity (continued). "Studies have found that overweight patients with PCOS have higher levels of tumor necrosis factor-α (TNF-α) than controls, and obesity would exacerbate this inflammation." (PMID 40410881, 2025). "Whereas a reduction in both IL-1β and TNF-α was observed in the overweight/pre-obesity population in the intervention group, an increase in both cytokines was found in the overweight/pre-obesity population in the control group." (PMID 40430061, 2025). "Obesity can promote the recruitment of proinflammatory macrophages, which secrete large amounts of TNF-α." (PMID 41333918, 2025). "Depression and obesity are highly comorbid and frequently co-occur with inflammation mediated by proinflammatory cytokines such as IL-6 and TNF-α." (PMID 40698360, 2025). "Chronic low-grade inflammation is an important feature of obesity, involving the accumulation of macrophages in adipose tissue and the recruitment of additional inflammatory factors such as TNF-α and IL-1β." (PMID 40308638, 2025). "TNF-α, a crucial pro-inflammatory mediator, is aberrantly overexpressed in the adipose tissues of patients with obesity and T2DM." (PMID 41137228, 2025). "In individuals with obesity, pro-inflammatory cytokines such as interleukin-6 (IL-6), IL-1β, and tumor necrosis factor-α (TNF-α) can upregulate hepcidin, a central regulator of iron homeostasis." (PMID 41141252, 2025). "In conclusion, this study identified three markers, Wnt5a, leptin, and TNF-α which were significantly higher in women with obesity and positively correlated with each other." (PMID 39837875, 2025). "Since adipocytes and preadipocytes are identified as reservoirs for proinflammatory cytokines, including TNF-α, IL-1, and IL-6, obesity is a chronic inflammatory condition." (PMID 40566527, 2025). "Under the effect of TNF-α in obesity-related SAP, the transcription and translation of IGF2BP3 in intestinal epithelial cells were inhibited, thereby affecting the expression of CLDN11." (PMID 39856555, 2025). "Inflammatory cytokines such as TNF-α, IL-1β, and IL-6 can reduce insulin sensitivity and promote obesity." (PMID 40298814, 2025). "Adipose tissue dysfunction in obesity triggers the release of pro-inflammatory cytokines (e.g., TNF-α, IL-6) and reduces adiponectin, an anti-inflammatory and insulin-sensitizing adipokine." (PMID 40181314, 2025). "In the setting of obesity, dysfunctional adipose tissue triggers the release of pro-inflammatory cytokines, including interleukin-6, tumor necrosis factor-α, and C-reactive protein." (PMID 41415798, 2025). "Chronic inflammation, which is particularly prevalent in obesity, generates a continuous influx of cytokines, such as TNF-α and IL-6, that maintain a self-reinforcing cycle of NF-κB activation and oxidative stress." (PMID 40002389, 2025). "In the pathogenesis of T2DM and obesity, inflammatory factors, particularly IL-6 and TNF-α, play a crucial role." (PMID 40842495, 2025). "Obesity stimulates adipose tissue to release inflammatory cytokines (IL-6, MCP-1, TNF-α), the levels of which are associated with prostate cancer progression in clinical studies." (PMID 40136652, 2025). "Driving neuroinflammation involves blood-brain barrier (BBB) dysregulation and elevated levels of pro-inflammatory cytokines, such as TNF-α and IL-6, which are excessively released during obesity." (PMID 40277905, 2025). "Interleukin‐6 (IL‐6), tumor necrosis factor alpha (TNF‐α), and irisin (cytokines) are affected by excess body fat (obesity), skeletal muscle, and resistance exercise (RE)." (PMID 40243109, 2025). "Obesity reduces the level of IL-10 (an anti-inflammatory cytokine), and this, along with overproduction of inflammatory mediators such as tumor necrosis factor-α and IL-6, leads to progression of MASLD." (PMID 40881517, 2025).
Obesity (continued). "This immunostimulatory role becomes pathological in obesity, where hyperleptinemia coexists with leptin resistance—a state exacerbated by pro-inflammatory cytokines like TNF-α that further impair leptin signaling." (PMID 40699756, 2025). "Elevated levels of IL-1ß and TNF-α are key players in chronic inflammatory diseases such as obesity, diabetes, rheumatoid arthritis and inflammatory bowel disease, among others, as well as periodontitis." (PMID 40430061, 2025). "Inhibition of IKKB, a component of the IKK/NF-κB pathway, has been shown to improve obesity-induced insulin resistance and reduce TNF-α production in animal models and in T2D." (PMID 41472730, 2025). "Obesity is now widely recognized as a chronic inflammatory state, with adipose tissue and free fatty acids fueling the production of TNF-α and related cytokines." (PMID 41150807, 2025). "6-Shogaol inhibited IL-1β secretion by blocking NLRP3 inflammasome activation and reduced TNF-α levels, demonstrating a relevant anti-inflammatory effect in the context of obesity." (PMID 40733199, 2025). "Secondly, IL-1β, IL-6, TNF-α, and IL-18 are overexpressed in obesity, contributing to the development of nephropathy by promoting inflammation." (PMID 40703753, 2025). "In contrast, obesity induces a shift from M2 to M1 macrophages, which secrete pro-inflammatory cytokines such as IL-1, IL-6, IL-12, TNF-α, and monocyte chemotactic protein-1 (MCP-1), and produce inducible nitric oxide synthase (iNOS)." (PMID 40725440, 2025). "We found that the levels of TNF-α in experimental obesity-related SAP were higher than IL-1β, IL-6, and IFN-γ, indicating its potential unique role." (PMID 39856555, 2025). "Adipose tissue expansion in obesity triggers chronic low-grade inflammation, characterized by an increased production of pro-inflammatory cytokines, including IL-6, IL-1, IL-8, and TNF-α, primarily by infiltrating macrophages." (PMID 40298814, 2025). "Adiponectin exerts anti-tumor activity by suppressing the secretion of pro-inflammatory cytokines, e.g., IL-6 and TNF-α, lessening the chronic inflammation related to obesity or the anti-inflammatory effect." (PMID 40227577, 2025). "In this study, we applied anti-TNFα therapy aimed at targeting the elevated TNF-α in obesity-related SAP." (PMID 39856555, 2025). "During obesity, these adipokines, along with tumor necrosis factor-alpha, interleukin [IL] - 1β, 6, 18, are found with increased serum levels." (PMID 40108925, 2025). "To achieve this, we utilized fully differentiated and hypertrophic SGBS cells as a cellular model of obesity, inducing insulin resistance and inflammation by exposing them to exogenous TNF‐α." (PMID 40951581, 2025). "Obesity further exacerbates this effect by creating a chronic inflammatory environment (with elevated TNF-α and IL-1β from adipose tissue) that synergizes with microbiota-driven inflammation." (PMID 41374093, 2025). "Animal trial suggested that deleting TNF-α protects from the obesity-related decrease in insulin receptor signaling in fat tissues and muscles, being a central factor contributing to insulin resistance in diet-induced obesity." (PMID 40565251, 2025). "Elevated levels of pro-inflammatory cytokines, such as TNFα and IL-6, which are commonly observed in obesity, can promote osteoclastogenesis through an NFκB-mediated pathway." (PMID 40260279, 2025). "Among the cytokines considered central to inflammatory processes is Tumor Necrosis Factor-α (TNF-α), currently regarded as the primary link between obesity, diabetes, and chronic inflammation due to its overexpression in the adipose tissue of obese mice." (PMID 41304906, 2025). "Obesity‐associated inflammation, characterized by increased CRP, IL‐6, leptin, and TNF‐α, further exacerbates endometrial cancer progression by enhancing cancer cell invasion and inhibiting apoptosis." (PMID 40922069, 2025).
Obesity (continued). "The WAT has also been extensively studied in the context of obesity, where it has been shown that pro‐inflammatory cytokines such as TNFα signal directly to adipocytes, leading to adipocyte insulin resistance." (PMID 39428707, 2025). "Inflammatory changes in the TNF system related to obesity that have been identified in overweight and obese children and adolescents reinforce the need for intervention with educational measures focused on weight loss." (PMID 40359199, 2025). "In individuals with obesity-related insulin resistance, hypertrophied adipocytes exhibit increased secretion of pro-inflammatory cytokines, such as TNF-α, IL-6, and IL-1β, all of which impair insulin signaling by activating NF-κB and JNK pathways." (PMID 40563357, 2025). "This pro-inflammatory state and cell imbalance observed in patients with obesity is the consequence of an increased production of adipokines, such as tumor necrosis factor alpha (TNF-a), interleukin-6 (IL-6), and C-reactive protein (CRP), by the adipocytes." (PMID 40435018, 2025). "Cytokines like TNF-α, IL-1β, and IL-6 not only fuel tumor growth in obesity-afflicted mouse models but also parallelly increase in obese women, closely correlating with the onset and progression of breast tumors." (PMID 40040878, 2025). "Paprika pigments have been reported to reduce the expression of obesity-related inflammatory markers, including interleukin-6 (IL-6), tumor necrosis factor-α (TNF-α), monocyte chemotactic protein-1 (MCP-1), and resistin in 3T3-L1 adipocytes." (PMID 39858523, 2025). "In obesity, adipose tissue becomes inflamed and dysfunctional, releasing excess free fatty acids (FFAs) and pro-inflammatory adipokines, including tumor necrosis factor α (TNF-α) and interleukin 6 (IL-6)." (PMID 40218971, 2025). "Individuals with obesity tend to have higher serum levels of tumor necrosis factor-alpha (TNF-α) and interleukin-6 (IL-6)." (PMID 41156096, 2025). "The term adipokine also encompasses molecules that are canonical players within the immune system, including cytokines like interleukin (IL)‐6 and tumour necrosis factor alpha (TNFα), which are elevated during obesity, and contribute to inflammation." (PMID 39428707, 2025). "In obesity, hyperleptinemia drives IL-6 and TNF-α while reducing adiponectin, fostering insulin resistance and constraining muscle fatty acid oxidation." (PMID 41002965, 2025). "Obesity is accompanied by chronic systemic inflammation and leads to an increase of IL-6 and TNF-α in plasma." (PMID 41224847, 2025). "Obesity-induced enhancement of TNF-α expression facilitates the development of colorectal cancer through various mechanisms." (PMID 40406485, 2025). "NF-κB, often activated by TNF-α in obesity-related EC, also regulates GLUT6, linking inflammation to metabolic reprogramming." (PMID 41383623, 2025). "TNF is also upregulated in multiple mouse models that are accompanied with obesity and metabolic complications." (PMID 38874196, 2025). "Leptin levels are typically elevated in individuals with obesity, leading to an upregulation of pro-inflammatory cytokines like TNF-a and IL-6." (PMID 40558305, 2025). "Alterations to cytokines and inflammatory markers have also been implicated with obesity and PCOS, including decreased adipokine levels and increased TNF-α and IL-6, contributing to increased steroidogenesis, hyperandrogenemia, and insulin resistance." (PMID 41295220, 2025). "Studies have shown that DAV supplementation can reduce the levels of pro-inflammatory cytokines such as TNF-α, IL-1, and IL-6, which are involved in the pathogenesis of various chronic diseases, including obesity." (PMID 39974837, 2025). "In obesity, increased infiltration of immune cells—particularly M1 macrophages and Th1/Tc1 lymphocytes—promotes the release of cytokines such as TNF-α, IL-6, and MCP-1." (PMID 41302933, 2025).
Obesity (continued). "Most obesity-related compounds in the blood are also in saliva, i.e., insulin, leptin, α-amylase, tumor necrosis factor α/interleukin 6, C-reactive protein, and adiponectin." (PMID 40565251, 2025). "On the other hand, the significant difference in serum TNF-α was found only between obesity classes I vs. III (p = 0.002)." (PMID 39837875, 2025). "There is a feedback loop explaining the increased production of multiple inflammatory cytokines (IL-6, IL-12, TNF-α) from leptin and the increased expression of leptin from others (e.g., IL-1, TNF-α), leading to a chronic inflammatory state due to obesity." (PMID 41227378, 2025). "This analysis evaluated the potential reciprocal relationships between the TNF-α -308 G/A gene polymorphism, the Composite Dietary Antioxidant Index (CDAI), and insulin-related variables in Spanish adults with obesity." (PMID 40732969, 2025). "Overall, the TNF-α/IGF2BP3/CLDN11 axis was involved in the mechanism of obesity-mediated SAP exacerbation and suggests potential therapeutic targets." (PMID 39856555, 2025). "By incorporating adiposity, TyG-BMI captures obesity’s contribution to IR—through pro-inflammatory adipokines (e.g., TNF-α, IL-6) and reduced adiponectin—amplifying systemic inflammation and metabolic dysfunction." (PMID 41141345, 2025). "HFD-induced obesity led to increased TNF-α, caspase-3, and Bax and decreased Bcl-2 expression levels in heart tissue." (PMID 40292260, 2025). "First, visceral fat in obesity acts as an active endocrine organ, secreting various pro-inflammatory cytokines such as tumor necrosis factor-α, interleukin-6, and IL-1." (PMID 41465937, 2025). "In obesity, hypertrophied adipocytes become metabolically dysregulated, secreting elevated levels of inflammatory cytokines including TNF-α, IL-6, and MCP-1, which contribute to systemic insulin resistance, endothelial dysfunction, and myocardial fibrosis." (PMID 41374408, 2025). "Inflammation is also present in cases of obesity in childhood and adolescence, especially caused by cytokines such as MCP-1, IL-6, TNF-α and IL-1β." (PMID 40002337, 2025). "As compared with individuals with normal weight, people with obesity exhibit higher postprandial glucose, insulin, TG, and inflammatory markers such as IL-6, TNF-α, and CRP." (PMID 41301434, 2025). "In this context, specific pro-inflammatory cytokines such as TNF-α, IL-1β, and IL-6 have emerged as key players in the pathophysiology of obesity and its complications." (PMID 41141350, 2025). "A significantly different behavior was shown between IG and CG in the overweight/pre-obesity subgroup for IL-1β (p = 0.014; Z = 2.430; r = 0.63) and TNF-α (p = 0.029; Z = 2.199; r = 0.57)." (PMID 40430061, 2025). "The chronic inflammatory state that characterizes obesity was reflected in the MS mice by increased TNF-α, IFN-γ, and IL-6 plasma levels." (PMID 40710566, 2025). "The initial report for obesity-related inflammation was from a study of elevated tumor necrosis factor (TNFα) in AT in an obese animal model." (PMID 40218960, 2025). "The TNF-α concentrations in the blood rise with increasing obesity and correlate with insulin resistance." (PMID 40565595, 2025). "The adipose tissue of individuals with obesity releases pro-inflammatory adipokines such as TNF and IL-1β." (PMID 41153608, 2025). "Visfatin, also elevated in obesity, exhibits pro-inflammatory effects including NF-κB activation and TNF-α production, promoting chronic inflammation relevant to cancer development." (PMID 41555998, 2025). "Tumor necrosis factor (TNFα) expression continues to be a clear link between innate immunity and obesity and metabolism." (PMID 40766326, 2025). "Chemerin also contributes to obesity-related inflammation by recruiting macrophages, dendritic cells, and NK cells and correlates with pro-inflammatory markers such as TNF-α, IL-6, and hs-CRP." (PMID 40564199, 2025). "In humans, both obesity and diabetic nephropathy are recognized entities for increased circulating TNFα." (PMID 40868832, 2025).